ISYNA1 (inositol-3-phosphate synthase 1)
Description:
Key enzyme in myo-inositol biosynthesis pathway that catalyzes the conversion of glucose 6-phosphate to 1-myo-inositol 1-phosphate in a NAD-dependent manner. Rate-limiting enzyme in the synthesis of all inositol-containing compounds.
Synonyms: IPS 1; INO1; INOS; IPS; IPS-1
Tractability: PROTAC: ubiquitination databases record sites on it; its protein half-life has been measured.
Gene: Protein-coding gene on chromosome 19 (18,434,388 to 18,438,178, reverse strand). Ensembl gene ENSG00000105655.
Subcellular location: Cytoplasm
Subcellular location (Human Protein Atlas): Nucleoplasm; Cytosol
Pathways (Reactome):
Metabolism: Synthesis of IP2, IP, and Ins in the cytosol
Gene Ontology:
Molecular function: inositol-3-phosphate synthase activity; protein binding
Biological process: inositol biosynthetic process; phospholipid biosynthetic process
Cellular component: cytoplasm; cytosol
Genetic constraint (gnomAD): Loss-of-function variants: 34 observed, 45.07 expected, observed/expected ratio (o/e) 0.75, 90% interval 0.57 to 1. The synonymous counts are far from expectation, so gnomAD's model fits this gene poorly and the ratio says little. Missense variants: 718 observed, 746.92 expected, observed/expected ratio (o/e) 0.96, 90% interval 0.9 to 1.02. Synonymous variants: 396 observed, 330.59 expected, observed/expected ratio (o/e) 1.2, 90% interval 1.1 to 1.3.
Homologues: Orthologues: macaque ISYNA1 (98% identical), pig ISYNA1 (92% identical), guinea pig ISYNA1 (89% identical), mouse Isyna1 (88% identical), rat Isyna1 (88% identical), chimpanzee ISYNA1 (82% identical), tropical clawed frog isyna1 (69% identical), Drosophila melanogaster Inos (60% identical), Caenorhabditis elegans inos-1 (50% identical).
Diseases named in the same sentence as ISYNA1 in open-access papers:
ISYNA1 is named in the same sentence as 38 diseases in open-access papers, as found by Europe PMC text mining. Sharing a sentence is not in itself a finding about the gene and the disease. The quoted sentences say what the papers report.
pancreatic cancer (4 papers, 2020 to 2024). "Zhou and colleagues found a positive correlation between ISYNA1 expression and the survival of patients with pancreatic cancer, and observed increased invasiveness in ISYNA1-silenced pancreatic cancer cells." (PMID 38384814, 2024). "And in multivariate analysis, the expression of MSI2 and ISYNA1 were independent unfavourable prognostic indicators for pancreatic cancer." (PMID 32779876, 2020). "In summary, MSI2 accelerates the development and progression of pancreatic cancer through a novel ISYNA1‐p21/ZEB‐1 pathway, which supplies a novel gene targets in the PC treatment." (PMID 32779876, 2020). "In current study, ISYNA1 was downregulated in pancreatic cancer tissues and was negatively related to MSI2 expression, T stage, vascular permeation and poor prognosis of PC patients." (PMID 32779876, 2020). "Immunofluorescence staining showed ISYNA1 was expressed in both nucleus and cytoplasm in pancreatic cancer cell lines, which was consistent with the results in IHC assays." (PMID 32779876, 2020). "Meanwhile, both qRT‐PCR and WB showed ISYNA1 mRNA and protein level in 29 paired fresh pancreatic cancer tissues were lower than that in corresponding normal pancreatic tissues, respectively (P < .01; P = .001)." (PMID 32779876, 2020). "Thus, the overexpression of MSI2 facilitates cell migration and cell invasion in pancreatic cancer by regulating ISYNA1‐ZEB‐1 pathway." (PMID 32779876, 2020). "Moreover, high expression of MSI2 with low ISYNA1 expression was found in serial pancreatic cancer sections and vice versa." (PMID 32779876, 2020).
bladder cancer (3 papers, 2021 to 2024). "Moreover, higher expression of ISYNA1 is associated with gliomas and bladder carcinoma." (PMID 35812748, 2022). "However, ISYNA1 plays the opposite role in bladder cancer, and its knockdown significantly promotes apoptosis of bladder cancer cells." (PMID 38384814, 2024).
brain tumors (2 papers, 2019 to 2020). "A recent in vivo survey supports this by demonstrating a link between myo-Inositol concentration and hypermethylation in the expression of inositol 3-phosphate synthase (ISYNA1) in brain tumors." (PMID 30791611, 2019). "Moreover, in brain tumors a link between M-ins levels and the expression of the enzyme inositol 3-phosphate synthase (ISYNA1) has been reported." (PMID 33212941, 2020).
central nervous system lymphomas (2 papers, 2020 to 2022). "The expression of ISYNA1 and myoinositol in gliomas was significantly higher than that in primary central nervous system lymphomas." (PMID 32779876, 2020).
colorectal adenocarcinoma (2 papers, 2022 to 2025). The most common type of colorectal carcinoma.
breast tumor (1 paper, 2022). "Here we found significantly lower methylation of CD160, ISYNA1 and RAD51B were correlated with hormone receptor status, increased breast tumor size, advanced tumor stage and more lymph node involvement." (PMID 35812748, 2022).
colon cancer (1 paper, 2023). "Conversely, in colon cancer, high expression of ISYNA1 has been linked to poor prognosis and resistance to most anticancer chemotherapy drugs." (PMID 37743471, 2023).
osteoarthritis (1 paper, 2024). A noninflammatory degenerative joint disease occurring chiefly in older persons, characterized by degeneration of the articular cartilage, hypertrophy of bone at the margins and changes in the synovial membrane. "Additionally, curcumin can exert therapeutic effects on osteoarthritis by targeting the PIP4K2C, INPP5J, ITPKA, ITPKB, ISYNA1, and PLCH2 proteins associated with inositol phosphate metabolism." (PMID 37938371, 2024).
cancer (8 papers, 2019 to 2022). A tumor composed of atypical neoplastic, often pleomorphic cells that invade other tissues. "In our study, we comprehensively analyzed the role of ISYNA1 using multi-omics data from the TCGA database for 33 cancers, including expression, clinical features, prognostic values, DNA methylation, copy number alteration (CNA), and mutation status of ISYNA1." (PMID 35237596, 2022). "In addition, ISYNA1 was lowly expressed in only four cancer types, such as KICH, KIRC, KIRP, and PRAD." (PMID 35237596, 2022). "We aim to explore the role of ISYNA1 in pan-cancer, especially in COAD." (PMID 35237596, 2022). "In addition, decreased ISYNA1 expression was observed in four cancer types, such as KICH, KIRC, KIRP, and PRAD." (PMID 35237596, 2022). "For the correlation between ISYNA1 and CNA, we found that ISYNA1 expression was positively correlated with CNA in 17 among 33 cancers types, indicating that the high CNA was one of the main causes of high ISYNA1 expression in pan-cancer, except in COAD." (PMID 35237596, 2022). "Our results suggested that age might be a confounder for the cancer associated aberrant methylation of CD160, ISYNA1 and RAD51B in the blood." (PMID 35812748, 2022). "After exclusion criteria were applied, six genes (GBA, ATG10, TRIM27, CD160, ISYNA1, RAD51B) were selected for validating the associations between DNA methylation and BC with MassARRAY EpiTyper assays in validation I (48 sporadic BC cases and 48 matched cancer-free female controls)." (PMID 35812748, 2022). "However, studies involved the role of ISYNA1 in malignant tumours remain scarce and controvertial." (PMID 32779876, 2020). "To explore the potential pathways for the potential involvement of ISYNA1 in tumor progression, we further conducted the GSEA of ISYNA1 using TCGA pan-cancer data." (PMID 35237596, 2022). "In our study, we observed significantly lower methylation of CD160, ISYNA1 and RAD51B in blood DNA of BC patients than that of cancer-free controls in the Chinese population." (PMID 35812748, 2022). "Differential expression of CD160, ISYNA1 and RAD51B has been correlated to the clinical characteristics in various types of cancer." (PMID 35812748, 2022). "Since age has impact on DNA methylation patterns, we next evaluated the relationship between the methylation levels of CD160, ISYNA1 and RAD51B and age in 272 sporadic BC cases and 272 cancer-free female controls combining validation I and validation II." (PMID 35812748, 2022). "Therefore, targeting ISYNA1 may be a potential cancer therapy method in COAD." (PMID 35237596, 2022). "In order to further explore the potential mechanism of the five key genes (APOC1, APOC1P1, ISYNA1, C7orf61 and APOE) and whether these genes functioned through common cancer pathways, we analyzed them using the GSCALite platform by pathway activity module." (PMID 35371313, 2022). "CD160, ISYNA1 and RAD51B have been involved in the development of various types of cancer." (PMID 35812748, 2022). "In addition, we also found that the promoter methylation level of ISYNA1 was negatively correlated with ISYNA1 expression in 31 among 33 cancers types, including COAD (r = −0.33), indicating that the promoter methylation level of ISYNA1 mainly affects ISYNA1 mRNA expression in OCAD." (PMID 35237596, 2022).
tumor (8 papers, 2020 to 2025). "We also found that ISYNA1 expression was positively correlated with the infiltration level of tumor-associated macrophages and tumor-associated fibroblasts in COAD." (PMID 35237596, 2022). "ISYNA1 (Inositol-3-phosphate synthase 1) was positively associated with tumor T stage and LNM of BCa patients." (PMID 33869048, 2021). "Since ISYNA1 is highly expressed in DU145 cells and to date, there are few studies on ISYNA1 in tumor research, especially PRAD." (PMID 40308606, 2025). "The results revealed that ISYNA1 expression was different in the various tumor stages in COAD, ESCA, HNSC, LIHC, READ, STAD, THCA, and ACC." (PMID 35237596, 2022). "We identified inositol‐3‐phosphate synthase 1 (ISYNA1) as a novel tumour suppressor regulated by MSI2." (PMID 32779876, 2020). "The high expression of ISYNA1 predicted the immunosuppressive TIME, which may lead to poorer survival of tumor patients with a high ISYNA1 expression in COAD." (PMID 35237596, 2022). "We further investigated ISYNA1 expression at different tumor stages." (PMID 35237596, 2022). "Through the analysis of the correlation between ISYNA1 expression and TME, we found that the scores of immune system-related pathways and tumor stroma-related pathways were higher in the high-ISYNA1 expression group in COAD." (PMID 35237596, 2022). "RT‐PCR detection of budding RTP gene‐expressions in PDX model post two times 8 Gy irradiation revealed that most RTP gene levels (CST3, CDC37, IGFBP6, ISYNA1, RN7SL2) increased on day 9 when RTP cells were significantly enriched and partial fell back on day 82 when tumor repopulated." (PMID 36658726, 2023). "To evaluate the expression of ISYNA1 only in tumor tissues from TCGA cohort, we found that ISYNA1 expression was highest in tumor tissues of UCS and lowest in tumor tissues of COAD compared with other tumor tissues." (PMID 35237596, 2022).
ISYNA1 also shares sentences with these, for which no sentence is quoted: Alzheimer disease (2 papers); bipolar disorder (2); glioma (2); infection (2); African sleeping sickness (1); breast carcinoma (1); cardiomyopathy (1); Charcot-Marie-Tooth disease (1); colon adenocarcinoma (1); diabetes (1); Diarrhea (1); Fundus dystrophy (1); heart failure (1); Immunodeficiency (1); liver steatosis (1); lung carcinoma (1); lung squamous cell carcinoma (1); macular dystrophies (1); nemaline myopathy (1); nephronophthisis (1); nephrotic syndrome (1); non-syndromic intellectual disability (1); ovarian carcinoma (1); Pan (1); rheumatoid arthritis (1); spina bifida (1); type 2 diabetes (1); vaginitis (1).